RNU6-694P (RNA, U6 small nuclear 694, pseudogene)
Gene: Small nuclear RNA gene on chromosome 9 (4,386,410 to 4,386,556, reverse strand). Ensembl gene ENSG00000200941.
Homologues: Orthologues: chimpanzee U6 (99% identical), macaque U6 (65% identical), rabbit U6 (58% identical), dog U6 (55% identical), mouse Gm25716 (46% identical). Paralogues in human: RNU6-1310P (61% identical), RNU6-1031P (60% identical), RNU6-179P (60% identical), RNU6-233P (60% identical), RNU6-1083P (59% identical), RNU6-43P (59% identical), RNU6-552P (59% identical), RNU6-668P (59% identical), RNU6-797P (59% identical), RNU6-984P (59% identical), RNU6-1091P (59% identical), RNU6-1094P (59% identical), and 1284 more.